LINC02925 (long independently transcribed non-coding RNA 2925)
Synonyms: RP3-439F8.1
Gene: Long non-coding RNA gene on chromosome 22 (46,537,892 to 46,557,010, forward strand). Ensembl gene ENSG00000234869.
Gene Ontology:
Biological process: SRP-dependent cotranslational protein targeting to membrane, signal sequence recognition
Cellular component: signal recognition particle, endoplasmic reticulum targeting